DENND1C (DENN domain containing 1C)
Description:
Guanine nucleotide exchange factor (GEF) which may activate RAB8A, RAB13 and RAB35. Promotes the exchange of GDP to GTP, converting inactive GDP-bound Rab proteins into their active GTP-bound form.
Synonyms: FAM31C; FLJ22757
Tractability: PROTAC: ubiquitination databases record sites on it; its protein half-life has been measured.
Gene: Protein-coding gene on chromosome 19 (6,467,207 to 6,482,557, reverse strand). Ensembl gene ENSG00000205744.
Subcellular location: Cytoplasm, cytosol; Cytoplasmic vesicle, clathrin-coated vesicle
Subcellular location (Human Protein Atlas): Cytosol; Centrosome; Nucleoplasm
Pathways (Reactome):
Vesicle-mediated transport: RAB GEFs exchange GTP for GDP on RABs
Gene Ontology:
Molecular function: guanyl-nucleotide exchange factor activity; protein binding; phosphatidylinositol phosphate binding
Biological process: endocytic recycling; endocytosis
Cellular component: cytosol; clathrin-coated vesicle
Genetic constraint (gnomAD): Loss-of-function variants: 64 observed, 77 expected, observed/expected ratio (o/e) 0.83, 90% interval 0.68 to 1.02. The upper end of that interval is the gene's LOEUF score, 1.02, which puts it in group 4 of 6, group 1 being the genes least tolerant of losing a copy. Missense variants: 980 observed, 974.63 expected, observed/expected ratio (o/e) 1.01, 90% interval 0.95 to 1.06. Synonymous variants: 384 observed, 395.5 expected, observed/expected ratio (o/e) 0.97, 90% interval 0.89 to 1.06.
Homologues: Orthologues: chimpanzee DENND1C (98% identical), macaque DENND1C (92% identical), pig DENND1C (79% identical), dog DENND1C (78% identical), rabbit DENND1C (77% identical), guinea pig DENND1C (74% identical), rat Dennd1c (70% identical), mouse Dennd1c (70% identical), tropical clawed frog dennd1c (43% identical), zebrafish dennd1c (36% identical), Drosophila melanogaster CG18659 (27% identical), Caenorhabditis elegans rme-4 (23% identical). Paralogues in human: DENND1A (39% identical), DENND1B (38% identical).
Diseases named in the same sentence as DENND1C in open-access papers:
DENND1C is named in the same sentence as 5 diseases in open-access papers, as found by Europe PMC text mining. Sharing a sentence is not in itself a finding about the gene and the disease. The quoted sentences say what the papers report.
lung carcinoma (1 paper, 2025). "Five prognostic genes, including HPSE, DENND1C, GRWD1, HLA‐DQA1, and PDXK, were identified to further develop a risk signature, which exhibited moderate power for forecasting the prognosis of lung cancer patients in training, testing, and validation sets." (PMID 41031217, 2025). "The exact actions of DENND1C have not been investigated in human cancers, including lung cancer." (PMID 41031217, 2025).
melanoma (1 paper, 2023). A malignant, usually aggressive tumor composed of atypical, neoplastic melanocytes. "In addition to melanoma, CYTH4, AOAH, DENND1C, TBC1D10C, EPSTI1, SERPINB8, and GIMAP7 stratify responders and non-responders to ICB in other cancer types." (PMID 36588164, 2023). "CYTH4, DENND1C, AOAH, TBC1D10C, EPSTI1, GIMAP7, and FASL (FAS ligand) were novel predictors of ICB therapy and displayed high level of correlations with multiple immune checkpoints in melanoma and across 30 human cancers." (PMID 36588164, 2023).
metastatic melanoma (1 paper, 2023). A melanoma that has spread from its primary site to another anatomic site. "CYTH4, DENND1C, AOAH, EPSTI1, and TBC1D10C expressions are upregulated in metastatic melanoma compared to primary tumors." (PMID 36588164, 2023).
cancer (2 papers, 2023 to 2025). A tumor composed of atypical neoplastic, often pleomorphic cells that invade other tissues. "CYTH4, AOAH, DENND1C, TBC1D10C, EPSTI1, SERPINB8, and GIMAP7 are novel and robust individual genes in predicting resistance to ICB in multiple cancer types." (PMID 36588164, 2023). "In a comparison to AXL with an established role in enhancing resistance to ICB, CYTH4, DENND1C, AOAH, EPSTI1, and TBC1D10C display a stronger correlation with immune checkpoints in human cancers." (PMID 36588164, 2023). "Additionally, CYTH4, DENND1C, AOAH, EPSTI1, and TBC1D10C exhibit strong correlations with a set of immune checkpoints not only in SKCM but also across a spectrum of human cancers." (PMID 36588164, 2023).
tumor (1 paper, 2026). "In vitro experiments confirmed DENND1C as a tumor suppressor, inhibiting LUAD cell proliferation, invasion, and migration." (PMID 41751408, 2026).